MICU1 (mitochondrial calcium uptake 1)
Diseases named in the same sentence as MICU1 in open-access papers (continued):
Sharing a sentence is not in itself a finding about the gene and the disease.
colon cancer (2 papers, 2017 to 2024). "Here, we focused on investigating the expression of MICU1, MICU2, and the MICU2/MICU1 ratio in colon tumors using the cohort published by TCGA." (PMID 39466877, 2024). "Interestingly, the MICU2/MICU1 ratio is significantly up-regulated in colon tumors of stage IV compared with tumors belonging to less aggressive stages." (PMID 39466877, 2024). "Thus, it is unlikely that differences in mitochondrial Ca2+ uptake between normal and colon cancer cells are due to differences in expression of MCU and/or its modulatory regulator MICU1." (PMID 28903423, 2017).
endothelial dysfunction (2 papers, 2023 to 2025). In vascular diseases, endothelial dysfunction is a systemic pathological state of the endothelium (the inner lining of blood vessels) and can be broadly defined as an imbalance between vasodilating and vasoconstricting substances produced by (or acting on) the endothelium. "To further examine the role of SIRT3 in endothelial dysfunction caused by MICU1 depletion, we silenced SIRT3 in HAECs." (PMID 40166941, 2025).
heart failure (2 papers, 2024 to 2025). Inability of the heart to pump blood at an adequate rate to meet tissue metabolic requirements. "In myocardial samples from patients with heart failure, MICU1 levels and the MICU1/MCU ratio are increased, which might explain the differences in MCU current measured in mitoplasts (i.e., mitochondria stripped of the outer membrane) isolated from myocardial samples of heart failure patients." (PMID 38890208, 2024).
hyperlipidaemia (2 papers, 2022). "Hyperlipidemia and hyperglycemia were discussed in a recent study in their relationship to inhibiting expression of transcription factor Sp1 which was shown to be involved in downregulating mitochondrial calcium uptake 1 (MICUI1)." (PMID 35252405, 2022). "In vitro data suggest that hyperglycaemia and hyperlipidaemia inhibited the expression of MICU1-regulating transcription factor Sp1, while MICU1 over-expression increases mitochondrial Ca2+ uptake and inhibits ROS production through enhancing the NADPH-dependent antioxidant system." (PMID 35887211, 2022).
migraine (2 papers, 2021 to 2022). "Aura prevalence reported in only 3 patients (10.7% of the migraineurs): 2 were typical auras, while 1 patient carrying MICU1 mutations experienced hemiplegic migraine." (PMID 35273322, 2022).
Myocardial fibrosis (2 papers, 2022 to 2023). "In conclusion, these data suggested that overexpression of MICU1 in CMECs significantly ameliorated myocardial fibrosis and improved left ventricular function in diabetic mice." (PMID 37592255, 2023).
Sepsis (2 papers, 2005 to 2016). Sepsis is defined as life-threatening organ dysfunction caused by a dysregulated host response to infection. "MICU1-targeted treatment may hold promise for preventing the progression of IAH to gut-derived sepsis." (PMID 27924224, 2016). "MICU1 may be a promising target for intervening in IAH-induced gut-derived sepsis and MOF." (PMID 27924224, 2016). "Further studies would be needed to establish whether MICU1 would be disrupted as the course/degree of IAH progresses, and to determine what roles are played by MICU1 in the subsequent abdominal compartment syndrome and gut-derived sepsis." (PMID 27924224, 2016).
Stroke (2 papers, 2023). Sudden impairment of blood flow to a part of the brain due to occlusion or rupture of an artery to the brain. "MICU1 plays an important role in the development of cancer, stroke, and genetic diseases, and maintaining endothelial function." (PMID 37592255, 2023). "Since MICU3 increases mitochondrial Ca2+ uptake by dimerizing with MICU1, drugs that reversibly disrupt the formation of MICU1/3 dimers may be a useful protective strategy for stroke." (PMID 37484823, 2023).
type 2 diabetes (2 papers, 2023 to 2024). "Mitochondrial calcium uptake 1 protein (MICU1) is a regulatory protein in the mitochondrial calcium uniporter complex, which regulates mitochondrial calcium [(Ca2+)m] levels in response to stress from obesity and type 2 diabetes." (PMID 39252788, 2024). "Interestingly, the MCUbW245R/V251E mutant was found to interact with MICU1, but similar to the proteomic data (see Section 3.1) WT MCUb did not interact with MICU1 in cardiomyocytes from the type 2 diabetic mouse hearts." (PMID 36538269, 2023).
bacterial pneumonia (1 paper, 2022). Acute infection of the lung parenchyma caused by bacteria (e.g., Streptococcus pneumoniae, Haemophilus influenzae, Chlamydia pneumoniae, Mycoplasma pneumoniae, and Legionella pneumophila). "Collectively, these data indicate that loss of Micu1 in AT2 cells inhibited AT2-to-AT1 cell differentiation, resulting in decreased pulmonary function and slow recovery of surviving animals from bacterial pneumonia." (PMID 35050901, 2022). "Deletion of Micu1 in AT2 cells reduces AT2-to-AT1 cell differentiation during steady-state tissue maintenance and alveolar epithelial regeneration after bacterial pneumonia." (PMID 35050901, 2022). "Deletion of Micu1 in AT2 cells reduced AT2 cell differentiation into AT1 cells during steady-state tissue maintenance and alveolar epithelial regeneration after bacterial pneumonia." (PMID 35050901, 2022). "Although MICU1-dependent mCa2+ uptake is important for AT2 cell plasticity in our mouse model of bacterial pneumonia, it is not possible from these experiments to extrapolate our findings to all species or all models of lung injury." (PMID 35050901, 2022).
Barth syndrome (1 paper, 2023). Barth syndrome (BTHS) is an inborn error of phospholipid metabolism characterized by dilated cardiomyopathy (DCM), skeletal myopathy, neutropenia, growth delay and organic aciduria. "MICU1 was also shown to be critical in another skeletal muscle disorder, the Barth syndrome, which is characterized by cardiolipin deficiency." (PMID 37759703, 2023). "This showed that cardiolipin is required for the stability of MICU1, which is reduced in Barth syndrome patient-derived cells, together with MCU and MICU2." (PMID 37759703, 2023).
brain malformations (1 paper, 2020). "The finding of multiple brain malformations on MRI suggests that MICU1 may be necessary for neuronal development and migration." (PMID 32395406, 2020).
cardiac interstitial fibrosis (1 paper, 2020). "Notably, MICU1 supplementation ameliorated the enlargement of cardiomyocytes, attenuated cardiac interstitial fibrosis, decreased the ratios of HW/TL and LVW/TL, and rescued cardiac dilation function in hypertrophic myocardium." (PMID 33259334, 2020).
cataract (1 paper, 2016). Partial or complete opacity of the crystalline lens of one or both eyes that decreases visual acuity and eventually results in blindness. "Based on the limited clinical descriptions published to date, our patients have a similar phenotype to patients with MICU1 substitutions, although cataracts have not been noted before (reference 11)." (PMID 27123478, 2016).
chronic lung disease (1 paper, 2022). According to the definitions of the American and British Thoracic Societies, including pulmonary functional tests, X-rays, and CT scans for items such as fibrosis, bronchiectasis, bullae, emphysema, nodular or lymphomatous abnormalities. "Additional studies are needed to assess whether regulation of AT2 cell plasticity by MICU1-dependent mCa2+ uptake can be implicated in chronic lung diseases as well." (PMID 35050901, 2022).
cognitive deficits (1 paper, 2023). "Loss-of-function mutations in MICU1 have been linked to a muscle and brain disorder characterized by muscle weakness, cognitive deficits, and abnormal involuntary movements including chorea, tremor, dystonic posturing, and orofacial dyskinesias." (PMID 37484823, 2023). "Unlike MICU1 deficiency, MICU2 truncation produces cognitive deficits without motor involvement." (PMID 37484823, 2023).
colon adenocarcinoma (1 paper, 2024). "In particular, using The Cancer Genome Atlas Colon Adenocarcinoma (TCGA-COAD) data set, the authors observed that the expression of MICU1 and MICU2 are respectively down- and up-regulated with stages." (PMID 39466877, 2024).
congenital myopathy (1 paper, 2019). "The first described patients with MICU1 mutations exhibit a severe, complex neurological condition accompanied by muscular dystrophy and congenital myopathy, clearly associated with mitochondrial dysfunction, whereas a later study reported MICU1 patients with a relatively mild fatigue syndrome." (PMID 31042479, 2019).
developmental disability (1 paper, 2020). Disorders in which there is a delay in development based on that expected for a given age level or stage of development. "Genetic variations in MICU1 and MICU2 have been reported to cause myopathy, developmental disability and neurological symptoms typical of mitochondrial disorders." (PMID 32395406, 2020).
energy metabolism disorder (1 paper, 2023). "We confirmed that the energy metabolism disorder of T2DM may be related to the mitochondrial dysfunction caused by the decreased expression of MCU and MICU1, and the abnormal mCa2+ uptake caused by the MCU-mediated mitochondrial dysfunction, which may be the pathogenesis of T2DM." (PMID 37337224, 2023).
facioscapulohumeral muscular dystrophy (1 paper, 2022). An autosomal dominant disorder affecting the skeletal muscles of the face, scapula, and upper arm. "We finally analyzed MICU1 alternative splicing events in patients affected by DM1 and we compared MICU1 alternative splicing events with those of muscles of patients affected by facioscapulohumeral muscular dystrophy (FSHD), a pathological condition where splicing is not affected." (PMID 35269658, 2022).
Hypertension (1 paper, 2020). The presence of chronic increased pressure in the systemic arterial system. "Meanwhile, blood pressure was indistinguishable between MICU1 knockdown and WT mice, suggesting that MICU1 do not affect Ang-II-induced hypertension." (PMID 33259334, 2020).
liver cancer (1 paper, 2020). An epithelial or non-epithelial malignant neoplasm that arises from the liver. "In addition, it does not affect the MICU2 levels, but it affects the mitochondrial Ca2+ uptake after the MICU1 gene is knocked down or overexpressed in liver cancer cells." (PMID 33114428, 2020). "Next, we analyzed the endogenous levels of CREB, MCU, MICU1, and MICU2 in liver cancer cells and normal liver cell lines, and the results showed that the mRNA expression levels of CREB, MCU, MICU1, and MICU2 in liver cancer cell lines were higher than that in normal liver cells." (PMID 33114428, 2020). "The mRNA levels of CREB, MCU, MICU1, and MICU2 were found to be significantly increased in liver cancer, indicating that these proteins may have potential carcinogenic effects." (PMID 33114428, 2020).
liver failure (1 paper, 2016). A liver disease characterized by the liver losing or has lost all of its function. "However, the complete protection against PHx-induced liver failure in MICU1 KD mice afforded by NIM811 treatment clearly points to PTP opening because of mitochondrial calcium overload as the cause of tissue injury." (PMID 26956930, 2016).
MELAS (1 paper, 2022). "Clinical phenotype was consistent with CPEO in 33 patients (5 CPEO, 25 CPEO plus and 3 KSS), MELAS in 6, ADOA in 1, other MM in 6 patients (a young patient with MICU1 gene mutation and other unspecified MM in 5 cases)." (PMID 35273322, 2022).
microcephaly (1 paper, 2022). A congenital or acquired developmental disorder in which the circumference of the head is smaller than normal for the person's age and sex.
Nystagmus (1 paper, 2022). Rhythmic, involuntary oscillations of one or both eyes related to abnormality in fixation, conjugate gaze, or vestibular mechanisms.
ovarian tumour (1 paper, 2017). "Since in vitro silencing of MICU1 pruned OvCa cells towards chemosensitization by cisplatin, therefore, we wanted to investigate whether a low dose of cisplatin could effectively inhibit ovarian tumour growth." (PMID 28530221, 2017).
pancreatic cancer (1 paper, 2017). "Finally, in pancreatic cancer MCU and MICU1 genes undergo loss of heterozygosity, although whether MCU and MICU1 are oncogenes or tumor suppressor genes still needs to be clarified." (PMID 28740830, 2017).
renal clear cell carcinoma (1 paper, 2024). "Manipulating MiCU1 expression enhances the growth and proliferation of renal clear cell carcinoma cells, whereas increasing MiCU1 levels markedly suppresses cell growth and proliferation." (PMID 38911376, 2024).
cancer (27 papers, 2014 to 2025). A tumor composed of atypical neoplastic, often pleomorphic cells that invade other tissues. "Genome-wide loss-of-function screening using cold-vulnerable human cancer cell lines revealed that disruption of MICU1, which positively regulates the transport of Ca2+ ions into the mitochondrial matrix, prevents cold-induced cell death." (PMID 39300059, 2024). "Similarly, increased calcium levels caused by SOCE activation in hepatocytes and cancer cells are associated with elevated ROS production and a higher rate of cell death in MICU1-knockout cells." (PMID 39769488, 2024). "Notably, global genomic analysis identified loss of heterozygosity for MCU and MICU1 in human pancreatic cancer tissues, hinting to an involvement of these genes in cancer progression." (PMID 33614647, 2021). "Taken together, we propose that association between MICU1/MICU1, MICU2/MICU1, and MICU3/MICU1 implicated in MCU regulation shape the metabolic orientation of cancer cells." (PMID 39466877, 2024). "This evidence underscores the potential of MiCU1/2 as promising targets for cancer immunotherapy and novel immune-related biomarkers for diagnosing and prognosticating BRCA." (PMID 38911376, 2024). "Reduced levels of the MICU1 protein in cancer cells have been shown to lead to increased mitochondrial calcium levels and increased ROS production, which in turn contributes to necroptotic death." (PMID 39769488, 2024). "In the context of cancer, it has been demonstrated that Akt phosphorylation of MICU1 elevates basal mitCa2+ level and, consequently, ROS production, contributing to cancer progression." (PMID 38148906, 2023). "MICU1 has been shown to be methylated by protein arginine methyltransferase 1 (PRMT1) in cancer cells, yielding decreased Ca2+ sensitivity and reduced Ca2+ entry." (PMID 35743109, 2022). "Under the condition of MICU1 methylation by PRMT1 in aging or cancer, UCP2 that binds to methylated MICU1 destabilizes CJ, disrupts SMPGs, and facilitates fast Ca2+ uptake via the CM." (PMID 35778442, 2022). "While the deregulation of expression varies in a cancer type-specific manner, in general, overexpression of MCU and loss of MICU1 expression are correlated with poor prognosis." (PMID 35490194, 2022). "Enhanced MICU1 expression has been found in many types of cancers, and it is related to poor clinical outcomes and increased glycolysis and chemoresistance." (PMID 33946271, 2021). "The crucial role of MCU regulators in cancer progression gets also obvious by the impact of MICU1 impairment, which results in the opening of MCU, enhanced mitochondrial Ca2+ uptake and ROS production in HeLa, and potentially boosts tumor growth." (PMID 33614647, 2021). "The study identified Mitochondrial Calcium Uptake 1 (MICU1) as an important component for cancer metabolism that influences aerobic glycolysis and chemoresistance and can have a potential role in cancer therapeutics." (PMID 34900668, 2021). "For instance, a recently described Akt kinase-mediated phosphorylation of MICU1 at the N-terminal region in cancer is the first demonstration of a phosphorylation event for the MICU1 subunit." (PMID 31569359, 2019). "In agreement, in melanoma, one of the most aggressive and lethal cancers, the knockdown of the ribosomal protein S3, reduced the expression of MICU1 allowing a mitochondrial Ca2+ overload that triggered apoptosis." (PMID 28944215, 2017). "Nevertheless, to ensure sufficient mitochondrial Ca2+ uptake, the uncoupling protein 2 (UCP2) is able to normalize mitochondrial Ca2+ uptake in case of PRMT1-driven methylation of MICU1 in cancer cells." (PMID 29113301, 2017). "Our results purport possible therapeutic application of MICU1 targeting as an innovative way to normalize aberrant metabolism in cancer to improve poor prognosis." (PMID 28530221, 2017).
cancer (continued). "Recently, we have shown that PRMT1-driven methylation of MICU1 desensitizes the mitochondrial Ca2+ uptake machinery and, therefore, reduces mitochondrial Ca2+ accumulation in cancer cells." (PMID 29113301, 2017). "Loss-of-function screening for suppressors of cold-induced ferroptosis in human cancer cell lines identified mitochondrial calcium uptake protein 1 (MICU1), a protein located in the inner mitochondrial membrane that is involved in the transport of Ca2+ to the mitochondrial matrix." (PMID 38725569, 2024). "MCU and MICU1 deregulations have been reported in several cancers." (PMID 35490194, 2022). "Indeed, studies have shown that increased or decreased MCU and MICU1 expression in different cancers contribute to tumourigenesis and metastasis in several ways." (PMID 35490194, 2022). "Altogether, both MCU and its negative regulator MICU1 may be considered important potential targets for combating cancer chemoresistance." (PMID 33946271, 2021). "Notably, the contribution of UCP2 to mitochondrial Ca2+ uptake is limited to conditions of enhanced PRMT1 activity and subsequent methylation of MICU1, as the case in most cancer cells." (PMID 33614647, 2021). "Thus, silencing of MICU1 reduces anchorage-independent clonal growth and cellular mobility in OvCa cells, two pivotal hallmarks of cancer progression." (PMID 28530221, 2017). "Present study defines a role of MICU1 in regulating drug resistance phenotype in cancer model." (PMID 28530221, 2017). "However, an increased PRMT1 activity also results in methylation of MICU1 and a reduced mitochondrial Ca2+ uptake/activity would counteract the elevated demand of cancer cells on Ca2+-triggered ATP production in the mitochondria." (PMID 27642082, 2016). "Thus, MICU1 is involved in cold-induced ferroptosis in certain types of cancer cells." (PMID 38725569, 2024). "Under conditions of elevated protein methyltransferase 1 (PRMT1), as the case in cancer or aging, UCP2 interacts with PRMT1-methylated MICU1 and re-establishes its Ca2+ sensitivity resulting in a normalization of mitochondrial Ca2+ uptake." (PMID 33614647, 2021). "Thus, we investigated the stoichiometry of MICU2/MICU1 and the molecular function of MICU2 in cancer cells by knocking down the MICU2 gene in CRC cells." (PMID 39466877, 2024). "In this pathway, MICU1 induces the accumulation of mitochondrial Ca2+ and the production of ROS, suggesting that the binding of MICU1 to the MCU is necessary for the function of the MCU complex and the entry of Ca2+ into mitochondria is a prerequisite survival factor of cancer cells." (PMID 35743109, 2022). "Besides, cancer cells tune their mitochondrial Ca2+ uptake very tightly by alterations in the expression and function of proteins involved in mitochondrial Ca2+ uptake and extrusion, including MCU, MICU1, MICU2, MCUR1, and NCLX." (PMID 33614647, 2021).